FGF19 (fibroblast growth factor 19)
Diseases named in the same sentence as FGF19 in open-access papers (continued):
Sharing a sentence is not in itself a finding about the gene and the disease.
colon cancer (21 papers, 2009 to 2025). "Evidence suggests that intestinal epithelial cells express receptors that recognize FGF19, such as FGFR4 and β-Klotho, and cultured mouse enteroids respond to FGF19 treatment and inhibition of FGF19 reduced growth and metastasis of colon tumor grafts." (PMID 41043692, 2025). "There is evidence in human colon cancer cell lines, colon tumor xenografts, and FGF19 transgenic mice that blocking selectively the interaction of FGF19 and FGFR4 using an anti-FGF19 monoclonal antibody has a potential pharmacological anti-tumorigenic effect." (PMID 34200439, 2021). "Blocking either FGF19 or FGFR4 significantly reduces in vivo xenograft tumor growth of colon cancer cells." (PMID 32154250, 2020). "PXR, when activated, has been shown to be sufficient at enhancing neoplastic characteristics including: cell growth, invasion, and metastasis through activation of Fibroblast Growth Factor 19 (FGF19) gene expression in colon cancer." (PMID 33076284, 2020). "Activation of PXR enhanced cell growth, invasion, and metastasis in human colon tumor cell lines and human colon cancer xenograft models via PXR-mediated FGF19 signaling." (PMID 24690092, 2014). "For the treatment of liver and colon cancer, and cancers related to head and neck squamous cells, inactivating FGF19 may counteract carcinomas." (PMID 37108717, 2023). "Another study in human colon cancer cell lines indicates that when FGF19 interacts with its receptor FGFR4, there is an increase in phosphorylated glycogen synthase kinase 3β (GSK3β), an intermediary of Wnt pathway, which actives β-catenin, that, in turn, causes loss of β-catenin-E-cadherin binding." (PMID 34200439, 2021). "An anti-FGF19 monoclonal antibody 1A6 acting to block the interaction of FGF19 with its receptor FGFR4 could inhibit the colon tumor xenografts in vivo." (PMID 32111983, 2020). "Hyperactivation of FGFR4 by FGF19 was reported in colon cancer cells and hepatocellar carcinoma." (PMID 32154250, 2020). "However, FGF19 signaling was only induced in colon cancer tissue, suggesting a PXR tumor specific mechanism of proliferation." (PMID 24690092, 2014). "Moreover, recent reports have revealed that a neutralizing antibody that selectively blocks the interaction of FGF19 with FGFR4 inhibits the growth of colon tumors and the formation of liver tumors in vivo." (PMID 22309595, 2012). "Knockdown of FGF19 in colon cancer cells decreased tumor growth in vitro and in vivo." (PMID 19948057, 2009). "Shown in both human colon tumor cell lines and in primary human colon cancer tissue xenografted into immunodeficient mice, the role of PXR activation through FGF19 induction mediates colon cancer cell proliferation and migration." (PMID 33076284, 2020). "In fact, anti-FGF19 antibody treatment is reported to reduce the growth of colon tumor xenografts and prevent HCC development in FGF19 transgenic mice." (PMID 31718608, 2019). "FGF19 is a recently identified driver gene in hepatocarcinogenesis and an activator of β-catenin signaling in HCC and colon cancer cells." (PMID 23285165, 2012). "Activation of β-catenin through the FGF19/FGFR4 system has been thoroughly characterized in human HCC and colon cancer cells." (PMID 23285165, 2012). "In contrast we observed that DCLK1 and FGF19 were colocalized in both colorectal cancer and NAT tissues supporting a role for their interaction in colon cancers but not PDAC." (PMID 40162222, 2025).
atherosclerosis (16 papers, 2013 to 2025). A disease characterized by the build-up of fatty material and calcium deposition in the arterial wall resulting in partial or complete occlusion of the arterial lumen. "The aim of this study was to investigate the association of circulating FGF19 levels with the development of subclinical atherosclerosis (subAS) in patients with T2D in a 3-year prospective study." (PMID 32528406, 2020). "The association of FGF19 with various metabolic disorders which are recognized as promoting factors of atherosclerosis development is well-studied." (PMID 23940810, 2013). "To date, however, only one study explored the association of FGF19 with the plasma atherosclerosis index (AIP; defined as log[TG/HDL-c]) which was a simple indicator of CAD." (PMID 23940810, 2013). "First, this study had a cross-sectional design based on a small sample size and could not explain any causal connection between the decreased serum FGF19 level and increased risk of atherosclerosis and CAD as assessed by baPWV and AIP." (PMID 32477430, 2020). "Third, although our data might suggest a causal relationship between circulating FGF19 levels and the development of subAS, further basic studies are warranted to examine the role of FGF19 in the pathogenesis of atherosclerosis." (PMID 32528406, 2020). "The serum FGF19 levels were independently and inversely associated with baPWV and AIP, which indicate that serum FGF19 may have a protective role in atherosclerosis in patients with T2D." (PMID 32477430, 2020). "Administration of the FGF-19 analog NGM282 reduces atherosclerosis in Apoe−/− mice, enhances plasma HDL-cholesterol in healthy subjects, and improved NASH and fibrosis in phase II clinical trials." (PMID 37200978, 2023). "Nevertheless, how FGF19 functions in atherosclerosis during the development of T2D is still unclear." (PMID 32528406, 2020). "Given these functions, FGF19 is a potential molecular in investigating human chronic disease, including T2D and atherosclerosis, in which glucose and lipid metabolism play a vital role." (PMID 32528406, 2020). "Previous studies have demonstrated the critical link between these metabolic processes and human chronic diseases including T2D and atherosclerosis and suggested FGF19 as an independent factor for T2D and coronary artery disease." (PMID 32528406, 2020). "Overall, this report reveals a previously undescribed role of FGF19 on cholesterol metabolism and offers a differentiated mechanism for the control of atherosclerosis progression." (PMID 30679232, 2019). "We also evaluated the effects of an FGF19 analog on aortic plaque and lesion formation in mouse models of atherosclerosis and on plasma cholesterol levels in healthy human volunteers." (PMID 30679232, 2019). "Based on these results, FGF19 analog NGM282 protects Apoe−/− mice from atherosclerosis following challenge with an atherogenic diet." (PMID 30679232, 2019). "Previous reports have shown negative associations between FGF19 and cardiovascular risk factors including triglycerides and the plasma atherosclerosis index." (PMID 39341924, 2024). "Atherosclerosis is directly related to the death-deriving diabetic macroangiopathy in T2D, yet relationships between FGF19 and atherosclerosis in T2D remain unclear." (PMID 32528406, 2020). "Our results revealed that FGF19 was an early predictor for atherosclerosis in men." (PMID 32528406, 2020). "In this study, we investigated serum concentration of FGF19 and early atherosclerosis events in human T2D patients to assess whether serum FGF19 could be applied in predicting atherosclerosis in T2D." (PMID 32528406, 2020). "The concentration of FGF19 was negatively correlated with the concentration of triglycerides (TG) and the plasma atherosclerosis index but was positively correlated to high-density lipoprotein cholesterol (HDL-c), which proved the vital importance of FGF19 in lipid metabolism and atherosclerosis." (PMID 32528406, 2020).
atherosclerosis (continued). "Several possible mechanisms may explain the link between FGF19 levels and atherosclerosis in T2D patients." (PMID 32477430, 2020). "The fibroblast growth factor 19 (FGF19) has been implicated in recent studies as a potential regulator of glucose and lipid metabolism, which may lead to atherosclerosis." (PMID 23940810, 2013). "We found that serum FGF19 may have a protective role in atherosclerosis in patients with T2D." (PMID 32477430, 2020). "Therefore, FGF19 may promote atherosclerosis by inhibiting the protective effect of PON-1." (PMID 32528406, 2020). "In contrast, by selective modulation of LXR activity, FGF19 and NGM282 can overcome this hurdle while attenuating inflammation and protecting against atherosclerosis." (PMID 30679232, 2019). "Patients with CAD have also been found to have lower levels of FGF19 than those without CAD, adjusting for other factors, while FGF19 was also an independent predictor of the extent of atherosclerosis." (PMID 36983851, 2023).
primary biliary cholangitis (15 papers, 2012 to 2026). Primary biliary cholangitis (PBC) is a chronic and slowly progressive cholestatic liver disease of autoimmune etiology characterized by injury of the intrahepatic bile ducts that may eventually lead to liver failure. "In (chronic) cholestatic liver disease (eg, primary biliary cirrhosis, alcoholic hepatitis, and biliary atresia), the bile salt-FGF19 axis is altered and associated with repressed bile salt synthesis, probably to prevent further hepatic bile salt overload." (PMID 38836805, 2024). "FGF15/19 is not physiologically expressed in the liver 32, but pathological FGF19 expression in liver tissues was detected in patients with hepatitis C virus-related cirrhosis or biliary cirrhosis." (PMID 34326695, 2021). "As previously reported, FGF15/19 is not physiologically expressed in the liver, but pathological FGF19 expression in liver tissues was detected in the patients with hepatitis C virus cirrhosis and with biliary cirrhosis, which are closely related to HCC." (PMID 29973237, 2018). "BA synthesis was directly quantified by measuring serum concentrations of 7alpha-hydroxycholest-4-en-3-one (C4), along with serum FGF19 and other parameters, in 44 patients with primary biliary cirrhosis (PBC) and 10 healthy subjects." (PMID 28570655, 2017). "A recent study also examined the use of serum and liver FGF19 levels as a biomarker for severity of primary biliary cirrhosis (PBC)." (PMID 27699175, 2016). "Novel farnesoid X receptor agonists (FXR), peroxisome proliferator-activated receptor (PPAR) agonists, and fibroblast growth factor 19 (FGF19) analogs are in development and may act as second-line therapy for primary biliary cholangitis refractory to UDCA." (PMID 38287391, 2024). "Similarly, a correlation between BA and FGF19 levels was also reported in patients with primary biliary cholangitis (PBC), suggestive towards a regulatory mechanism to suppress BA synthesis." (PMID 38332428, 2024). "Whether fibroblast growth factor 19 (FGF19) or farnesoid X receptor (FXR) dependent signaling are involved in the regulation of BA homeostasis in primary biliary cirrhosis (PBC) remains unknown." (PMID 26293907, 2015). "Also, the hepatic FGF19-Src-FXR pathway is defective in primary biliary cirrhosis (PBC) patients." (PMID 29968724, 2018). "Finally, we present intriguing data that the hepatic FGF19-Src-FXR phosphorylation signaling axis is likely defective in primary biliary cirrhosis (PBC, also known as primary biliary cholangitis) patients." (PMID 29968724, 2018). "Of note, based on increase of plasma FGF19 levels, magnitude of FXR stimulation with CDCA 15 mg/kg in the current study appears similar to 10 mg 6-ethyl-chenodeoxycholic acid in primary biliary cirrhosis (the dose currently proposed in this cholestatic liver disease)." (PMID 23189156, 2012).
Cirrhosis (14 papers, 2015 to 2025). A chronic disorder of the liver in which liver tissue becomes scarred and is partially replaced by regenerative nodules and fibrotic tissue resulting in loss of liver function. "Biologics based on the structure of fibroblast growth factor (FGF) 19 and 21 show strong beneficial effects in the treatment of metabolic dysfunction–associated steatotic liver disease (MASLD), including compensated cirrhosis." (PMID 40937171, 2025). "Systemic BA and FGF19 levels correlated significantly (r = 0.461; p < 0.001) and increased with cirrhosis severity." (PMID 38332428, 2024). "More importantly, consistent with our findings, FGF19 has been reported to be associated with the development of liver diseases, including HBV-related cirrhosis and hepatocellular carcinoma, possibly via FGF19-FGFR4 pathway-related immune dysregulation." (PMID 36532504, 2022). "In our study, FGF19 levels were highest in NHc but the increase of FGF19 was more likely related to carcinogenesis than to cirrhosis." (PMID 32352707, 2020). "In the ileum, expression of FXR, SHP and FGF19 decreased in patients with cirrhosis, and interestingly, intestinal FGF19 expression was not linked to systemic FGF19 levels." (PMID 38332428, 2024). "Although FGF19 was produced primarily in the ileum, it could be autocrined by hepatocellular under cholestatic conditions and peritumoral tissues cirrhosis." (PMID 27447573, 2016). "In addition, the HCC harboring FGF19 amplification is believed a switch from intestine-driven endocrine to autocrine by hepatocellular signaling in liver under cirrhosis." (PMID 27447573, 2016). "The current report shows for the first time that serum levels of FGF19 are notably elevated in PBC-AIH OS patients, especially patients with cirrhosis." (PMID 32626734, 2020). "In this report, BA synthesis was directly quantified by measuring serum concentrations of 7alpha-hydroxycholest-4-en-3-one (C4), along with serum FGF19 and other relevant parameters, in patients with PBC and PBC with cirrhosis." (PMID 28570655, 2017). "FGF19, FGFR4 and EpCAM expressions between the different histologic stages of fatty liver steatohepatitis-cirrhosis-HCC carcinogenesis sequence were compared to healthy hepatic tissue." (PMID 27447573, 2016). "Our group of PBC women also showed reduced levels of FGF19 than CTRL but similar to patients with NAFLD, probably due to optimal disease control and absence of cirrhosis; indeed, FGF19 serum levels are elevated in PBC non‐responders to UDCA or with advanced fibrosis, but decrease in UDCA responders." (PMID 36287108, 2023). "Serum levels of FGF19 were unrelated to age, gender and presence of cirrhosis (data not shown)." (PMID 26293907, 2015). "Interestingly, FGF-19 expression is increased in cirrhotic patients, therefore we speculate that the increased FGF-19 could lead to elevation of FXR-Y67 phosphorylation in cirrhosis patients." (PMID 34646233, 2021). "Therefore, the high levels of serum FGF19 in HCC patients could be both ileum-derived and hepatocellular derived by autocrine in the presence of pro-tumorigenic and tumorigenic conditions, including NASH, cirrhosis and HCC, but further study, again, is needed." (PMID 27447573, 2016). "Based on these data, we observe a strong negative correlation (r = -0.735, p < 0.0001) between serum levels of FGF19 and C4 in all PBC patients (with or without cirrhosis)." (PMID 28570655, 2017).
colorectal cancer (14 papers, 2010 to 2026). A primary or metastatic malignant neoplasm that affects the colon or rectum. "Moreover, chronically increased FGF19 level has also been reported to increase the risk for both colorectal cancer and cholangiocarcinoma in IBD patients which may have relevant clinical implication." (PMID 32565779, 2020). "Recent research shows FGF19 induces ELF4 in colorectal cancer, driving metastasis via ELF4‐mediated FGFR4 and Src kinase signaling." (PMID 41287970, 2025). "These promote liver colonization of CRC cells and support FGF19‐targeting therapy for colorectal cancer liver metastasis." (PMID 37345586, 2023). "FGF19 can promote the occurrence of colorectal cancer by regulating metabolic biological functions, such as bile acid biosynthesis and insulin resistance." (PMID 36751636, 2023). "Mechanistic study shows tumor-associated fibroblasts (TAF) -derived FGF19 is required for TAF-induced FGFR4/Wnt activation and governs colorectal cancer cell metastasis in vivo." (PMID 26498355, 2016). "It has been reported that the anti-FGF19 antibody 1A6 represses β-catenin activation in colorectal cancer xenograft models and an engineered FGF19 (M70) inhibits FGF19-dependent tumorigenesis but retains the ability to maintain bile acid homeostasis." (PMID 26498355, 2016). "More recently, TNFα, Hepatocyte Growth Factor, PDGF and FGF19 and IL-1β have been shown to activate Wnt/β-catenin signaling, the oncogenic pathway activated in the majority of colorectal cancers." (PMID 20661477, 2010). "Similarly, measurements of betanerve growth factor levels (GCST90274762; IVW: OR [95%CI] = 0.894 [0.801–0.997], P = .043), as well as Fibroblast growth factor 19 levels (GCST90274787; IVW: OR [95%CI] = 0.842 [0.7350.963], P = .012), indicated their linkage to colorectal cancer." (PMID 39612465, 2024).
liver fibrosis (14 papers, 2015 to 2025). "In clinical trials, liver fibrosis in nonalcoholic steatohepatitis patients was attenuated by FGF19 analogue treatment." (PMID 32587612, 2020). "Given that FGFs are associated with pulmonary fibrosis and renal fibrosis, we investigated the influence of the FGF19 serum levels on liver fibrosis." (PMID 31718608, 2019). "Recently, many clinical studies have found correlations between serum FGF19 levels and severity of hepatic fibrosis of multiple etiologies." (PMID 27699175, 2016). "FGF15, a mouse ortholog of human FGF19, may ameliorate liver fibrosis by improving hepatic and systemic metabolism." (PMID 40475534, 2025). "Several experiments have demonstrated that FGF19 exerts a protective effect against liver fibrosis." (PMID 32587612, 2020). "In addition, a strong correlation between the serum FGF19 levels and the liver fibrosis stage was detected in this study." (PMID 32626734, 2020). "As FGF19 is a negative feedback factor for bile acid synthesis, the observed hepatic fibrosis and inflammation in patients with low serum concentrations of FGF19 may have been the result of dysregulated bile acid production and bile acid toxicity." (PMID 27699175, 2016). "Moreover, intestinal‐specific agonist Fex and recombinant FGF19 protein could attenuate bile acid accumulation and reverse vancomycin‐induced liver fibrosis." (PMID 39680750, 2025). "Deletion of FGFR4 and Fgf15 (murine orthologue of FGF19) leads to significant liver fibrosis compared with little mates, suggesting that the FGFR4/FGF19 axis has antifibrotic properties." (PMID 32587612, 2020).
non-alcoholic fatty liver disease (14 papers, 2011 to 2025). "Contradictory findings are available about the association of FGF21 and FGF19 with nonalcoholic fatty liver disease (NAFLD) in humans." (PMID 23840612, 2013). "The important metabolic role of FGF15/19 is reflected by the following: the dysregulation of FGF19 has been associated with inflammatory bowel disease, type II diabetes, obesity, non-alcoholic fatty liver disease (NAFLD), and in a wide range of cholestasis spectrum." (PMID 34200439, 2021). "Clinically, pediatric patients with non-alcoholic fatty liver disease (NAFLD) have demonstrated decreased FGF19 levels." (PMID 35116006, 2021). "FGF19 concentration is also reduced in obese adolescents with non-alcoholic fatty liver disease (NAFLD), when compared to healthy subjects." (PMID 30927227, 2019). "In another study, patients with T2DM and nonalcoholic fatty liver disease treatment with semisynthetic derivative of CDCA led to enhanced serum FGF19 levels and improved insulin sensitivity." (PMID 28729691, 2017).